ALB (albumin)
Diseases named in the same sentence as ALB in open-access papers (continued):
Sharing a sentence is not in itself a finding about the gene and the disease.
Stroke (continued). "On the one side, this association may reveal a novel component linked to stroke pathophysiology and offer insight into how albumin may play a role in this process." (PMID 37682189, 2023). "This study highlights the association of serum calcium, albumin-corrected calcium, and ionic calcium with the size of acute ischemic stroke as well as severity outcome in terms of the National Institutes of health stroke scale (NIHSS) Score and Barthel Index." (PMID 37674968, 2023). "It has been proven that low albumin is linked to stroke and atrial fibrillation severity." (PMID 36739380, 2023). "It has been reported that low cholesterol levels in older adults might be a surrogate for nutritional deficiencies, a precursor to low serum albumin, and a sign of debilitating disease and, thus, a predisposing factor to increased stroke mortality." (PMID 37198718, 2023). "Of particular note, in a meta-analysis of 63 cohort studies and 20 randomized controlled trials (RCT), the risk of stroke increased by 7% for every 10 mL/min/1.73 m2 decline in eGFR and by 10% per 25 mg/mmol increase in the albumin–creatinine ratio independently of GFR." (PMID 37760839, 2023). "With respect to the analytical results, only albumin could be assessed, with low albumin being a risk factor for stroke in patients (MD − 3.18, 95% CI − 4.06 to − 2.31; p < 0.00001; participants = 6260; studies = 2; I2 = 96%)." (PMID 37848510, 2023). "This study assessed the relationship between serum albumin levels and adult stroke risk." (PMID 37682189, 2023). "We discovered an inverse relationship between blood albumin amounts and stroke risk." (PMID 37682189, 2023). "For example, the percentage of LDL lipids composed of cholesterol was the biomarker with the strongest association with stroke (hazard ratio: 0.89, 95% confidence interval: 0.86–0.91, P-value: 2 × 10−15) above and beyond that of albumin (HR: 0.83, 95% CI: 0.79–0.87, P-value: 5 × 10−13)." (PMID 36720882, 2023). "However, the stroke ChP showed loss of overall retention of albumin in the blood vessel but increased albumin immunosignals in the cytosol of CPEC." (PMID 38107410, 2023). "Serum albumin levels and the risk of stroke were negatively correlated." (PMID 37682189, 2023). "Associations between serum albumin concentration and stroke." (PMID 37682189, 2023). "Besides glucose/HbA1c ratio, glucose/glycated albumin ratio was shown to be associated with an increased risk of stroke in patients with a minor ischemic stroke or transient ischemic attack." (PMID 35725369, 2022). "Thus, the aim of the present study was to examine the associations of albumin-corrected calcium levels with vascular recanalization, symptomatic intracranial haemorrhage (sICH) and functional outcome in stroke patients after mechanical thrombectomy." (PMID 36056314, 2022). "Compared with the middle tertile (8.7–9.1 mg/dl), the multivariate-adjusted odds ratios (95% CIs) of first total stroke associated with the lowest tertile and the highest tertile of serum albumin-corrected calcium were 1.37 (1.10, 1.70) and 1.30 (1.04, 1.62), respectively." (PMID 35989922, 2022). "Risk of first stroke (total and subtypes) associated with serum albumin-corrected calcium levels*." (PMID 35989922, 2022). "However, reduced serum levels of albumin were also associated with a lower risk for CV complications (MI, HF and stroke) during ICU among these patients." (PMID 35850629, 2022). "In this prediction model, ALB was significantly associated with stroke recurrence." (PMID 35756923, 2022). "Higher levels of albumin were associated with lower stroke severity and better clinical outcomes." (PMID 34572977, 2021). "This small but systematic study has some important implications but additional studies are required to address the importance of monitoring albumin level and to determine the effect of traditional cardiovascular disease risk factors and their impact on outcome in stroke patients." (PMID 33959442, 2021).
Stroke (continued). "As such, our findings of enhanced GAD, albumin and cav-1 immunoreactivity at 5–6 days post-stroke suggest a loss of barrier integrity at this time-point, precipitating the development of vasogenic cerebral edema, extensive midline shift and the subsequent rise in ICP seen in this model." (PMID 31338013, 2019). "It suggests that patients with low serum albumin level within 24 h after the onset of stroke may have a poor functional outcome and it may be caused by low neuroprotective effects." (PMID 30046235, 2018). "Another reason may be that the vascular permeability increase that leads to the loss of albumin increases after stroke due to the complex cascade of secondary brain damage, such as inflammatory injury, OS, and cytotoxic damage." (PMID 30430305, 2018). "Decreased albumin levels are additionally linked to a higher risk of stroke and coronary heart disease, and may be a marker of inflammation, which is very dangerous to the mother and her baby." (PMID 27548057, 2016). "In the adjusted model, older age, arthritis, stroke, chronic bronchitis, congestive heart failure, cancer, and lower serum albumin level were significantly associated with self-reported limitation in walking between rooms, independent of measured performance on the 8-foot walk test." (PMID 20707890, 2010). "ALB may serve as a biological indicator for risk stratification during stroke rehabilitation." (PMID 41798801, 2026). "Furthermore, the EACH score can indirectly provide optimal targets for minimizing perioperative stroke risk for key correctable laboratory indicators such as albumin, electrolyte, and glucose by highlighting detailed trends in blood tests that increase risk nonlinearly." (PMID 40106818, 2025). "Numerous studies have shown an inverse relationship between serum albumin levels and the risk of various cardiovascular and cerebrovascular conditions in the general population, including coronary artery disease, heart failure, atrial fibrillation, stroke, and venous thromboembolism." (PMID 40917659, 2025). "Semaglutide reduced CV death/MI/stroke by 18% [hazard ratio (HR) 0.82 (95% confidence interval 0.68–0.98); P = .03], with consistency across estimated glomerular filtration rate categories, urine albumin-to-creatinine ratio levels, and KDIGO risk classification (all P-interaction > .13)." (PMID 39211948, 2025). "Recently, the RDW to albumin ratio (RAR), which was a combined index of RDW and serum albumin, has been reported to be provided more accurate risk prediction for adverse outcomes among various populations, including heart failure, acute coronary syndrome, stroke, and sepsis." (PMID 37737253, 2023). "Therefore, high CRP levels and low serum albumin may be also associated with poor neurological outcomes in neurocritically ill patients with stroke." (PMID 36079002, 2022). "Previously in a mouse model of stroke, it was found that microglia played a pathogenic role surrounding and phagocytosing endothelial cells leading to the disintegration of vessels, which was in part stimulated by fibrinogen or albumin, both indices of vessel leakage." (PMID 31708792, 2019). "This study mainly explores the association between red cell distribution width to albumin ratio (RAR) and all-cause mortality in stroke survivors, which is helpful for the prognostic management of stroke survivors." (PMID 41517762, 2026). "Advanced age, low BMI, stroke, ARDS, AKI, malignancy, elevated white blood cell count, and reduced platelet count or albumin levels are independent risk factors for in-hospital mortality in this population." (PMID 40177286, 2025). "In terms of the relationship between serum albumin and depression, studies on elderly stroke survivors showed that low serum albumin levels appeared to be associated with poststroke depressive symptoms." (PMID 40182647, 2025).
Stroke (continued). "Compared with the Control Group, the ObeseGroup had a greater prevalence of smoking history and a history of hypertensionor stroke, higher peripheral levels of triglycerides and total cholesterol, andlower peripheral levels of albumin (p < 0.05)." (PMID 40857628, 2025). "The combined use of neutrophil count and albumin levels has shown potential in improving the accuracy of stroke outcome predictions, integrating both acute inflammatory responses and nutritional status." (PMID 39935611, 2025). "Albumin can mediate systemic inflammation and exerting antioxidant activity, thereby protecting brain tissues and influencing the chance of recovery after stroke." (PMID 40353064, 2025). "C-Reactive Protein (CRP), Albumin (ALB), fibrinogen, and d-dimer are also closely related to inflammation and have been associated with stroke and mortality in AF patients." (PMID 40073613, 2025). "Our multivariate analysis identified advanced age, lower BMI, stroke, ARDS, AKI, malignancy, WBC count, and PLT or albumin levels as independent risk factors associated with mortality." (PMID 40177286, 2025). "Advanced age, low BMI, stroke, ARDS, AKI, malignancy, elevated WBC, decreased PLT, and low albumin were independent risk factors for in-hospital mortality." (PMID 40177286, 2025). "Chitosan/Fe3O4-encapsulated albumin NPs yield increased signal intensity in the infarcted myocardium, thereby facilitating the detection of analogous pathological features post-stroke." (PMID 39852564, 2025). "For example, numerous studies have shown that ratios such as neutrophil-to-albumin ratio, fibrinogen-to-albumin ratio, C-reactive protein to albumin ratio and High serum lactate dehydrogenase to albumin ratio are closely related to stroke." (PMID 40371078, 2025). "We have innovatively discovered that albumin (ALB) can serve as a new independent predictive factor for post-stroke CRPS." (PMID 40400911, 2025). "The FAR also reflects the inflammatory process of fibrinogen and additionally reflects nutritional status via albumin levels in cancer, heart failure, diabetic neuropathy, and stroke." (PMID 40806813, 2025). "Freedom from any stroke was also significantly greater in the normal albumin group (91.6% vs. 75.1%, p = 0.004)." (PMID 40943953, 2025). "In recent years, the role of the albumin-to-globulin ratio (A/G ratio) in stroke research has gained increasing attention." (PMID 40070476, 2025). "Two studies examined the relationship between albumin and stroke-related sarcopenia and showed that albumin was related to stroke-related sarcopenia." (PMID 41281355, 2025). "The effect of folic acid intervention also significantly reduced stroke risk in patients with the CC/CT MTHFR genotype and in male patients with elevated serum calcium levels (albumin-corrected serum calcium ≥2.43 mmol/L)." (PMID 40218880, 2025). "ALB has emerged as a strong marker of prognosis in individuals suffering from cardiovascular disease and stroke." (PMID 41411727, 2025). "Serum ALB plays neuroprotective roles in stroke, such as defending against oxidants and lowering hematocrit levels." (PMID 40028204, 2025). "On day 1, the TBI/stroke group had higher hemoglobin, hematocrit, lymphocytes, total protein, and albumin, but lower blood urea nitrogen (BUN), creatinine, and glucose." (PMID 40732927, 2025). "Reduced serum albumin is connected to multiple cardiovascular issues, such as myocardial infarction, heart failure, and stroke." (PMID 41536368, 2025). "Albumin levels have been recognized as reliable biomarkers for predicting mortality and functional recovery in stroke patients." (PMID 39935611, 2025). "Due to its relatively long half-life, serum albumin reflects a patient’s nutritional status before stroke onset." (PMID 39835151, 2024). "Research is underway to ascertain the ability of serum albumin to forecast the prognosis of stroke patients effectively." (PMID 38846203, 2024).
Stroke (continued). "Decreased levels of serum albumin, known as hypoalbuminemia, have been observed in patients with severe forms of myocardial infarction (MI) or injury, heart failure (HF), stroke, hip fracture, malignancy, and renal disease." (PMID 38580915, 2024). "Research on the relationship between NPAR and stroke is relatively limited, previous studies have predominantly focused on either neutrophil count or serum albumin individually." (PMID 39711045, 2024). "Hypoalbuminemia occurs not only in patients with TBI but also in critically ill patients on ICU and patients with stroke; lower albumin levels correlate with poor outcomes and a higher mortality rate." (PMID 38791046, 2024). "Further study and extensive clinical investigations are necessary to assess the therapeutic efficacy of serum albumin levels in predicting the outcomes of ischemic strokes and determining their suitability for inclusion in standard stroke therapy." (PMID 38846203, 2024). "The first point is that GPS uses only two serum parameters [albumin and C-reactive protein (CRP)] to predict outcomes, but the risk of stroke in these patients is multicausal." (PMID 39292095, 2024). "This study identifies a nonlinear, positive association between the neutrophil percentage‐to‐albumin ratio (NPAR) and stroke risk." (PMID 39711045, 2024). "The link between serum albumin levels and severe impairment of ADLs among stroke patients shows an inflection point around 38.0 g/L." (PMID 39835151, 2024). "By clarifying this, the study seeks to enhance understanding of serum albumin as a potential marker for stroke prognosis." (PMID 40655892, 2024). "Serum albumin has emerged as a significant prognostic marker in various conditions, including stroke." (PMID 40655892, 2024). "Stroke patients with higher albumin levels have a better prognosis compared to those with lower levels." (PMID 38699426, 2024). "Albumin levels measured within 24 h of admission are less likely to be affected by the acute stress of stroke." (PMID 39835151, 2024). "Albumin is also an important marker of nutritional status and inflammatory burden, both mediators of adverse stroke outcomes." (PMID 38794724, 2024). "Albumin inhibits thrombus development and leukocyte adhesion in the microvasculature during a stroke's reperfusion." (PMID 38846203, 2024). "In particular, finerenone has been shown to reduce urinary albumin-to-creatinine ratio (uACR) and lower the incidence of adverse outcomes such as heart failure hospitalizations, stroke, and kidney failure." (PMID 39541086, 2024). "After adjusting for confounding factors, the multivariate analysis revealed a 7% decrease in severe impairment of ADL after stroke for every unit (g/L) increase in serum albumin levels." (PMID 39835151, 2024). "Threshold effect analysis of neutrophil percentage‐to‐albumin ratio on stroke using a two‐piecewise linear regression model." (PMID 39711045, 2024). "Low serum albumin was reported to be a predictor of adverse outcomes in patients with chronic heart failure, stroke and coronary artery disease." (PMID 39902029, 2024). "Within 24 hours of stroke onset, laboratory tests were performed, including measurements of albumin, hemoglobin, lymphocytes, and platelet count." (PMID 39347246, 2024). "Threshold effect analysis of the relationship of serum albumin with severe impairment of ADL among stroke patients." (PMID 39835151, 2024). "Serum albumin is a commonly used nutritional index, and several studies have revealed that it serves as a predictive index for the prognosis of patients with stroke." (PMID 39097679, 2024). "All studies denoted some concern of bias related to the fluctuating nature of post-stroke albumin levels and reliance on a single exposure reading." (PMID 38794724, 2024). "Due to the high rate of missing NIHSS and TOAST data, we found a more robust association between serum albumin and severely impaired ADL of stroke after the multiple interpolation of NIHSS and TOAST." (PMID 39835151, 2024).
Stroke (continued). "The potential pathophysiological or therapeutic roles of albumin in patients with stroke warrant further investigation." (PMID 38323429, 2024). "During the acute stroke phase, albumin represents one of the most important systems that counteract the detrimental effect of the inflammatory response associated with neuronal injury." (PMID 38323429, 2024). "They employed unpaired t-tests to compare serum albumin levels between different dependency groups as defined by the Barthel index, both on the seventh day and third month after stroke." (PMID 40655892, 2024). "Overall, 320 111 patients with stroke had normal albumin levels (70.9±14.7 years; 48.9% females) and 183 729 (57.4%) had reduced albumin levels (72.9±14.3 years; 50.3% females)." (PMID 38323429, 2024). "The objective of this research is to examine the association between neutrophil percentage‐to‐albumin ratio (NPAR) and stroke, providing a reference for the prevention and prognosis of clinical stroke." (PMID 39711045, 2024). "Demographics, vascular risk factors, National Institutes of Health Stroke Scale (NIHSS) scores (admission and day three), modified Rankin scores (day 10), urinary albumin-to-creatinine ratios, and carotid artery Doppler studies were collected." (PMID 38752035, 2024). "Higher doses of albumin were associated with a dose-dependent reduction in the incidence of vasospasm, DCI, and stroke at 90 days." (PMID 38967704, 2024). "Three previous meta-analyses found that probiotics significantly increased the levels of TP, ALB, PA, and Hb in stroke patients, supporting the findings of the present study." (PMID 39050623, 2024). "From the linear regression analysis, the recovery of post-stroke patients in terms of variations in ADLs (ΔmBI) appeared to correlate with the “second dish” and albumin levels at admission, even after correcting for age." (PMID 39519422, 2024). "This evidence pointed to a strong link between albumin levels, the onset of stroke, progression of complications, and the outcome." (PMID 38699426, 2024). "To fill this knowledge gap, we evaluated the relationship between severe ADL limits and serum albumin levels, as well as the dose–response relationship between the two, in stroke patients." (PMID 39835151, 2024). "In the threshold analysis, the odds ratio (OR) for severe impairment of ADLs among stroke patients with serum albumin levels less than 38.0 g/L was 0.680 (95% CI: 0.568–0.814, p < 0.001)." (PMID 39835151, 2024). "The results of this study suggest that increasing serum albumin levels can significantly help improve the severity of ADL impairment in stroke patients, particularly those with serum albumin levels below 38.0 g/L." (PMID 39835151, 2024). "The strength of our study lies in its novel exploration of the association between serum albumin levels and severe ADL impairment following stroke, including the first discussion of their dose–response relationship." (PMID 39835151, 2024). "This study aims to investigate the relationship between serum albumin levels and stroke severity and outcomes in patients with acute ischemic stroke (AIS)." (PMID 40655892, 2024). "One hemorrhagic event was observed in the albumin group, while the control group experienced 4 deaths, 2 cases of ischemia, 1 pulmonary embolism, and 1 stroke." (PMID 39612427, 2024). "Further, to assess leakage of albumin into the CSF, we performed ELISA to measure the amount of albumin in CSF and serum of the sham control and tMCAO mice at 1 and 5 days post-stroke." (PMID 38107410, 2023). "The study further explored the predictive effects of GNRI, NIHSS, BMI, and Albumin on poor outcome in convalescence stage for patients with stroke." (PMID 36973674, 2023). "Subsequent logistic regression analysis with sarcopenia as the dependent variable and age, proportion of women, BMI, DBP, eGFR, serum albumin level, HbA1c, smoking status, stroke, and DVS for each food group as independent variables was performed." (PMID 38068851, 2023).